TF (transferrin)
Diseases named in the same sentence as TF in open-access papers (continued):
Sharing a sentence is not in itself a finding about the gene and the disease.
glioblastoma (49 papers, 2008 to 2026). The most malignant astrocytic tumor (WHO grade IV). "TF subserves other growth enhancing aspects of glioblastoma growth in addition to contributing to the excess thrombosis related morbidity associated with glioblastoma." (PMID 25211298, 2014). "In this study, we found that TF effectively reduces the proliferation of A1207 glioblastoma cells with an EC50 value of 13.7 μM, which is equal to the EC50 value of CX-4945, which was the first CK2 inhibitor in clinical phase II trials (13.9 μM)." (PMID 41828892, 2026). "Information on transferrin, ferroportin, ferroreductase, transferrin receptor, ferritin and others would have provided a more complete picture of the iron pathways in glioblastoma tumours." (PMID 40123902, 2025). "This strategy is also explored for the treatment of glioblastoma as the Tf receptor is abundantly distributed in glioblastoma and blood−brain barrier cells, and many studies have developed transferrin-modified nanosystems for glioblastoma therapy." (PMID 40867257, 2025). "By modifying nanoparticles to interact with receptors overexpressed on glioblastoma cells, such as transferrin, drug accumulation at the tumor site can be enhanced." (PMID 39744562, 2025). "Briefly, plasma membrane fractions of resected human glioblastoma samples were isolated and incubated with 125I-labeled transferrin." (PMID 38287054, 2024). "The authors also modified the PEGylated resveratrol–liposome (RES–LP) particles with parts of transferrin (Tf) for targeting Tf receptors on glioblastoma." (PMID 37237914, 2023). "In an air–liquid interface co-culture model with glioblastoma cells (U87), transferrin-decorated nanoparticles showed a faster passage through the epithelial cell layer as well as increased cellular uptake into glioblastoma cells." (PMID 36207657, 2023). "We found that PN glioblastoma stem cells (GSCs) secreted both DA and TF, which in turn supported the proliferation of neighboring MES GSCs." (PMID 35710828, 2022). "Studies on ANG-functionalized drug delivery systems have demonstrated that ANG has a higher BBB transcytosis efficacy and glioblastoma accumulation than lactoferrin, transferrin, and avidin." (PMID 33482822, 2021). "Transferrin molecules were added to the surface of the liposomes to enhance uptake from glioblastoma cells." (PMID 34681170, 2021). "We also found that in glioblastoma cells where p52SHC3 levels were increased, internalization of transferrin, an accepted indicator of clathrin-dependent vesicles recycling, was significantly increased compared to the same cells with baseline p52SHC3." (PMID 32443613, 2020). "Since transferrin is up-regulated in glioblastoma, this makes Tf–RES–L able to be site-specifically targeted." (PMID 31766544, 2019). "Receptors for transferrin (TfRs) are overexpressed on various tumors, including carcinomas, glioblastomas, and medulloblastomas." (PMID 31681205, 2019). "Tf-CRM107, a conjugate of human transferrin and diphtheria toxin, has been tested after intraventricular injection in a phase-II study on 44 patients with glioblastoma or astrocytoma." (PMID 31861465, 2019). "The nanosystems surface was modified using transferrin molecules to enhance uptake from glioblastoma cells." (PMID 30524273, 2018). "Drug targeting by conjugating with protein such as transferrin has been extensively studied, as a targeting molecule transferrin helps the transport of drug to glioblastoma which contains abundant transferrin receptors on the surface." (PMID 30374421, 2018). "In vitro competitive binding experiments with glioblastoma cells from humans proved that modification with transferrin molecules enhanced the cellular uptake by taking advantage of the transferrin receptor-mediated endocytic pathway." (PMID 30524273, 2018). "Quantum dots conjugated with transferrin have been used as a fluorescent probe to target transferrin receptors in glioblastoma cells." (PMID 27800481, 2016).
glioblastoma (continued). "Here, we propose a new strategy to treat glioblastoma based on transferrin (Tf)-targeted self-assembled nanoparticles (NPs) incorporating zoledronic acid (ZOL) (NPs-ZOL-Tf)." (PMID 25431953, 2014). "For example, early growth response gene-1 (EGR-1) regulates TF expression under hypoxic conditions in glioblastoma multiforme." (PMID 24086497, 2013). "Some examples are in a phase II clinical trial, transferrin fused to tetanus toxoid protein showed 30% of responders in glioblastoma patients, leading to the approval of a phase III trial." (PMID 18231595, 2008). "Taken together, TF in combination with TMZ may be a promising candidate for the treatment of glioblastoma in the future." (PMID 41828892, 2026). "Transferrin-modified magnetic NPs have also been applied to promote the entry of small interference RNA against polo-like kinase I (siPLK1) into the brain in the context of glioblastoma." (PMID 38794182, 2024). "Furthermore, the application of transferrin-modified magnetic NPs has demonstrated the accumulation of siPLK1 within the brain tissue of glioblastoma-bearing mice, together with a significant reduction in the tumor mass and improved survival of the mice." (PMID 38794182, 2024). "Interestingly, the JNK and the ERK1/2 signaling pathways induce TF gene expression in glioblastoma cell lines by enhancing AP-1 transcriptional activity." (PMID 38201433, 2023). "Finally, transferrin is a glycoprotein responsible for iron ion delivery that is overexpressed in glioblastoma, leading to increased cell proliferation and worsening prognosis." (PMID 36497269, 2022). "Paraneoplastic syndromes are a known consequence of many tumors, and glioblastomas in particular may upregulate the production of transferrin." (PMID 35314642, 2022). "Likewise, in vitro experiments of competitive binding of glioblastoma cells from humans showed that the addition of the transferrin molecules enhanced cellular uptake via the transferrin receptor-mediated endocytic pathway." (PMID 34681170, 2021). "In addition, TF expression in glioblastoma cells mediated by EGFR overexpression or EGF stimulation was JNK1 dependent." (PMID 34205482, 2021). "Using transferrin for the active targeting, transferrin receptors are upregulated in glioblastoma." (PMID 32290224, 2020). "Previous studies showed that HIF-1α knockdown enhanced hypoxia-induced TF expression in human glioblastoma cells, endothelial cells, and podocytes, suggesting that HIF-1α may act to prevent excessive expression of TF in response to hypoxic conditions." (PMID 30634531, 2019). "Captopril mediated down-regulation of glioblastoma cell overexpression of TF might be an ideal way to deprive glioblastomas of this growth and migration enhancing system." (PMID 25211298, 2014). "EGFR and PTEN modulate TF expression through JunD/AP-1 in glioblastoma." (PMID 24086497, 2013). "In another study, resveratrol encapsulated in transferrin-targeted liposomes was examined as an anti-glioblastoma (GBM) agent." (PMID 40650253, 2025). "Moreover, glioblastomas display increased amounts of ferritin, which is the iron storage protein, and may epigenetically upregulate the production of transferrin itself." (PMID 35314642, 2022). "We investigated the effect of TF and temozolomide (TMZ) as a single or combination treatment in two glioblastoma cell lines, A1207 and U87." (PMID 41828892, 2026). "This system can bind to free transferrin in the blood to prolong the circulation time and remain stable when crossing the BBB and targeting glioblastoma." (PMID 41287092, 2025). "Functionalization with transferrin, for instance, enabled BTNPs to target the transferrin receptor (TfR), commonly overexpressed on the surface of various cancer cells, including glioblastoma multiforme (GBM)." (PMID 41012541, 2025).
glioblastoma (continued). "For example, paclitaxel-loaded liposomes conjugated with the transferrin (TfR) receptor and RGD peptide have shown higher rates of cellular uptake and have efficiently targeted the αvβ3 integrins expressed by glioblastoma." (PMID 35163563, 2022). "Interestingly, resveratrol-loaded transferrin-modified PEGylated liposomes inhibited tumor growth and improved survival in mice suggesting their application could be a valuable strategy for the treatment of glioblastoma." (PMID 32290224, 2020). "In another work, a transferrin-targeted, RES-loaded liposome (Tf–RES–L) was produced to treat glioblastoma." (PMID 31766544, 2019). "Furthermore, transferrin-modified biomimetic liposomes enabled BBB penetration and prolonged survival in glioblastoma-bearing mice." (PMID 41287092, 2025). "Glioblastoma cancer stem cells expressed a higher level of transferrin (receptor transferrin receptor 1) than did nonglioblastoma cancer stem cells." (PMID 37433225, 2023). "To confirm that the reprogrammed TF network during MT is indeed clinically significant, we performed immunohistochemical (IHC) staining in a glioblastoma tumour microarray with 40 clinical WHO grade IV glioblastoma specimen serial paraffin‐embedded sections." (PMID 35851726, 2022). "Therefore, in the future study, transferrin carried small nucleic acids like miR-124 mimics, targeting the transferrin receptor on BBB might be a potential strategy to treat glioblastoma." (PMID 39865088, 2025).
Sepsis (45 papers, 2010 to 2025). Sepsis is defined as life-threatening organ dysfunction caused by a dysregulated host response to infection. "Increased transferrin saturation and decreased total iron‐binding capacity were linked to higher risks of bacterial pneumonia and sepsis." (PMID 40501500, 2025). "Neutrophils mediated the impact of serum iron and transferrin saturation on susceptibility to bacterial pneumonia and sepsis." (PMID 40501500, 2025). "Immunohistochemical staining showed that sepsis significantly upregulated the levels of ferritin and transferrin, indicating increased iron storage and transport associated with ferroptosis." (PMID 39857660, 2024). "Conversely, low transferrin levels were significantly associated with increased risk of sepsis (OR = 0.94, 95%CI = 0.86–1.02, p = 0.023)." (PMID 34869523, 2021). "Our findings showed evidence that genetic predisposition to higher levels of serum iron, ferritin, and transferrin saturation was causally associated with a higher risk of sepsis." (PMID 34869523, 2021). "The primary MR analyses by fixed-effects IVW showed a significant causal effect of serum iron, ferritin, and transferrin saturation on the risk of sepsis." (PMID 34869523, 2021). "Aberrant in vivo TF expression plays a pivotal role in the activation of blood coagulation in the setting of sepsis and endotoxemia 103, and the high incidence of sepsis-associated DIC is well known." (PMID 32792851, 2020). "This idea is in line with other studies demonstrating that high serum iron and TF-Sat as well as serum ferritin were associated with mortality from sepsis." (PMID 33014378, 2020). "A number of acute-phase proteins, such as C-reactive protein (CRP) and fibrinogen, rise after serious injury or sepsis in association with a drop in serum albumin, transthyretin, and transferrin." (PMID 20490277, 2010). "Single-SNP MR analyses showed that SNPs rs1800562 (HFE) and rs855791 (TMPRSS6) were associated with a significant effect of serum iron or transferrin saturation on sepsis, while SNPs rs1800562 (HFE) and rs2413450 (TMPRSS6) were significantly related to the causal effect of ferritin on sepsis." (PMID 34869523, 2021). "Moreover, serum transferrin levels <150 mg/dl were associated with an increased risk of sepsis in burn patients." (PMID 30038422, 2018). "TF mediates hemostasis upon vessel injury, but infection and other proinflammatory stimuli can trigger rapid F3 induction in macrophages to provoke aberrant coagulation, with inflammation-associated coagulation an underlying driver of sepsis-associated coagulopathies." (PMID 37316487, 2023). "Consistent with the increased H3K14la levels, expression levels of both VCAM‐1 and TF, two biomarkers of EC activation, were decreased by 2DG and oxamate pretreatment, indicating the alleviation of sepsis‐induced pulmonary EC activation." (PMID 39822760, 2025). "Transferrin and lymphocyte numbers decrease in sepsis and were positively correlated in the patients with severe illness, which is principally in line with the role of transferrin for lymphopoiesis." (PMID 39200147, 2024). "Only transferrin concentration varied between patients with sepsis (Me 141, IQR 117–186 mg/dL) versus patients with septic shock (Me 116, IQR 86–147 mg/dL); p = 0.008." (PMID 37046922, 2023). "In the early stages of sepsis, insufficient balance of TFPI in TF‐dependent coagulation events supports impaired physiological functions of anticoagulants identified during sepsis." (PMID 38020710, 2023). "Interleukin-1 (IL-1), IL-6, C-reactive protein and other inflammatory mediators stimulate TF expression on the surface of endothelial cells under inflammatory conditions such as sepsis and acute lung injury, leading to hypercoagulability." (PMID 37693903, 2023). "Although platelet-derived EVs represent the major population of EVs in sepsis, endothelial cells, monocytes, neutrophils, and red blood cells were extensively studied and shown to participate in TF-positive EV expression." (PMID 36013171, 2022).
Sepsis (continued). "The iuc is related to sepsis since it promotes bacterial growth in blood via the acquisition of iron from transferrin." (PMID 36558729, 2022). "The upregulation of TF expression in EVs was evident in EVs released from activated monocytes, endothelial cells, and platelets, and predicts the severity of sepsis." (PMID 36013171, 2022). "Several observational studies showed that patients with sepsis had significantly elevated levels of serum iron, ferritin, and transferrin saturation, but transferrin level was in the opposite direction." (PMID 34869523, 2021). "Elevated TF expression in neutrophils and the release of NETs decorated with TF have been found not only in COVID-19 but also in patients with sepsis, ST-segment elevation acute myocardial infarction (STEMI) and SLE." (PMID 34359859, 2021). "Initial conservative treatment is always required to optimize the general health of the patients by correcting nutritional status, replacement of fluid and electrolytes, improvement of serum albumin and transferrin and most importantly to control sepsis." (PMID 34040778, 2021). "Particularly low serum transferrin values occur in individuals with sepsis or acute-on-chronic liver failure." (PMID 33593348, 2021). "Enhanced levels of TF-carrying EV have been observed in cancer patients, in patients with unstable angina, and in patients with severe infections/sepsis." (PMID 30521543, 2018). "This suggests that sepsis triggers the activation of transferrin on the mitochondrial membrane of cardiomyocytes, which transports iron ions into the mitochondria, disrupting iron metabolism balance within them and ultimately inducing ferroptosis in cardiomyocytes." (PMID 40723819, 2025). "Additionally, studies have shown that iron and transferrin levels increase significantly in sepsis-induced lung injury, and MDA levels rise." (PMID 40723819, 2025). "For example, TF expression in monocytes and endothelial cells occurs predominantly during inflammation or thrombogenesis and pathological conditions such as sepsis, atherosclerosis and cancer can result in aberrant TF expression within the vasculature and cause thrombotic complications." (PMID 39331637, 2024). "Accordingly, serum iron and transferrin, an iron-transporting protein, are low in sepsis." (PMID 39200147, 2024). "Our findings also revealed that levels of apolipoprotein A, total cholesterol, and transferrin were significantly decreased in sepsis patients, while levels of cystatin C, rheumatoid factor, TIBC, CA19-9, ESR, PSA, CA125, tPSA, and hydroxybutyrate dehydrogenase were markedly elevated." (PMID 38835774, 2024). "In addition, fistula output, nutrition status, transferrin levels, and sepsis were the factors that prevented spontaneous closure." (PMID 38032483, 2023). "The results of our study show that ferroptosis was exacerbated in animal and cellular models of sepsis, as demonstrated by the decrease in the protein expression of Gpx4, increase in the protein expression of TF and FTH-1, and increase in serum Fe2+ levels compared with the sham groups." (PMID 37375325, 2023). "Among them, TF, an N-glycosylated glycoprotein in the acute stage of AP, has been shown to be at a lower level during sepsis; therefore, it was speculated that changes in TF could reflect the intensity of the inflammatory response." (PMID 35745003, 2022). "However, during sepsis, activated endothelium increase in TF expression within the vasculature is considered a pivotal step in initiating and sustaining coagulation." (PMID 34150806, 2021). "Genetic predisposition to sepsis did not appear to influence any of the studied iron status markers concentration (serum iron, ferritin, transferrin saturation, and transferrin)." (PMID 34869523, 2021). "In particular, transferrin emerges as a mortality predictor in sepsis and multiple liver disorders." (PMID 33593348, 2021).